MIR924 (microRNA 924)
Synonyms: hsa-mir-924; MIRN924
Gene: MicroRNA gene on chromosome 18 (39,622,123 to 39,622,175, reverse strand). Ensembl gene ENSG00000283615.
Gene Ontology:
Biological process: miRNA-mediated post-transcriptional gene silencing